GAA (alpha glucosidase)
Description:
Essential for the degradation of glycogen in lysosomes. Has highest activity on alpha-1,4-linked glycosidic linkages, but can also hydrolyze alpha-1,6-linked glucans.
Synonyms: IOPD; LOPD; LYAG
Tractability: Small molecule: an approved drug acts on it; a structure with a bound ligand is known; a high-quality ligand is known; it belongs to a druggable protein family. Antibody: its Gene Ontology location is reachable by antibodies, with high confidence; UniProt predicts a signal peptide or a membrane-spanning region. PROTAC: ubiquitination databases record sites on it; its protein half-life has been measured; a small molecule that binds it is known.
Target class: Enzyme; Hydrolase
Chemical probes: ML201, ML247
Gene: Protein-coding gene on chromosome 17 (80,101,533 to 80,119,881, forward strand). Ensembl gene ENSG00000171298.
Subcellular location: Lysosome; Lysosome membrane
Subcellular location (Human Protein Atlas): Vesicles
Pathways (Reactome):
Disease: Glycogen storage disease type II (GAA)
Immune System: Neutrophil degranulation
Metabolism: Glycogen breakdown (glycogenolysis)
Gene Ontology:
Molecular function: alpha-1,4-glucosidase activity; alpha-glucosidase activity; glucan 1,6-alpha-glucosidase activity; carbohydrate binding; hydrolase activity, hydrolyzing O-glycosyl compounds
Biological process: diaphragm contraction; glycogen catabolic process; glycophagy; lysosome organization; glucose metabolic process; maltose metabolic process; sucrose metabolic process; carbohydrate metabolic process; disaccharide metabolic process
Cellular component: extracellular exosome; lysosomal membrane; lysosome; membrane; azurophil granule membrane; ficolin-1-rich granule membrane; lysosomal lumen; plasma membrane; tertiary granule membrane; autolysosome lumen
Genetic constraint (gnomAD): Loss-of-function variants: 88 observed, 104.25 expected, observed/expected ratio (o/e) 0.84, 90% interval 0.71 to 1.01. The upper end of that interval is the gene's LOEUF score, 1.01, which puts it in group 4 of 6, group 1 being the genes least tolerant of losing a copy. Missense variants: 1,350 observed, 1,318.6 expected, observed/expected ratio (o/e) 1.02, 90% interval 0.98 to 1.07. Synonymous variants: 572 observed, 564.43 expected, observed/expected ratio (o/e) 1.01, 90% interval 0.94 to 1.09.
Gene-disease validity (ClinGen):
ClinGen rates the evidence that GAA causes each of these diseases.
glycogen storage disease II (autosomal recessive): Definitive. Glycogen storage disease due to acid maltase deficiency (AMD) is an autosomal recessive trait leading to metabolic myopathy that affects cardiac and respiratory muscles in addition to skeletal muscle and other tissues.
Homologues: Orthologues: chimpanzee GAA (99% identical), macaque GAA (95% identical), dog GAA (84% identical), guinea pig GAA (83% identical), rat Gaa (82% identical), pig GAA (81% identical), mouse Gaa (80% identical), tropical clawed frog gaa (60% identical), Caenorhabditis elegans aagr-2 (32% identical), zebrafish GAA (30% identical), zebrafish gaa (25% identical), Caenorhabditis elegans aagr-4 (24% identical), and 2 more. Paralogues in human: MGAM (42% identical), MGAM2 (40% identical), SI (40% identical), GANAB (27% identical), GANC (26% identical), MYORG (14% identical).
Diseases named in the same sentence as GAA in open-access papers:
GAA is named in the same sentence as 169 diseases in open-access papers, as found by Europe PMC text mining. Sharing a sentence is not in itself a finding about the gene and the disease. The quoted sentences say what the papers report.
Pompe disease (149 papers, 2008 to 2026). "It is intriguing that lysosomal glycogen storage and impaired autophagy are typical hallmarks of an inborn lysosomal storage disorder, Pompe disease, due to acid α‐glucosidase (GAA) deficiency." (PMID 41554119, 2026). "Complete or near-complete GAA deficiency leads to classical Pompe’s disease, characterized by foetal involvement, life-threathening neonatal hypertrophic cardiomyopathy, and severe hypotonia." (PMID 41316280, 2025). "Glycogen storage disease type II, or Pompe disease, is a genetic disorder where GAA enzyme activity is deficient and autolysosomal (autophagosome and lysosome) glycogen accumulates." (PMID 40108792, 2025). "Pompe disease (PD) is an autosomal recessive lysosomal storage disorder caused by the deficient activity of acid alpha glucosidase (GAA) enzyme due to mutations in the GAA gene." (PMID 39905333, 2025). "Glycogen storage disease type II (MIM #232300), commonly known as Pompe disease (PD), is an autosomal recessive progressive neuromuscular disorder induced by a deficiency in lysosomal acid α-glucosidase (GAA, EC 3.2.1.20)." (PMID 40869986, 2025). "Late-onset Pompe’s disease (LOPD) is a progressive treatable metabolic myopathy due to partial acid α-glucosidase (GAA) deficiency, with potential onset during the pediatric age." (PMID 41316280, 2025). "Glycogen storage disease II (GSDII, OMIM 232300), or Pompe disease, is a rare autosomal recessive disorder caused by the enzymatic deficiency of the alpha-1,4-glucosidase (GAA or acid maltase) which is deputed to the glycogen degradation within lysosomes." (PMID 40626179, 2025). "Pompe disease is a rare autosomal-recessive neuromuscular disorder caused by a deficiency of the lysosomal enzyme acid alpha-glucosidase (GAA), leading to the pathological accumulation of glycogen and impaired autophagy." (PMID 40843676, 2025). "Pompe disease (glycogen storage disease type II) is a disorder of glycogen metabolism caused by deficiency of the lysosomal enzyme acid alpha-glucosidase (GAA)." (PMID 40136631, 2025). "Pompe disease can be detected by screening newborn infants for deficiency of the GAA enzyme and confirmed through genetic testing." (PMID 40981304, 2025). "Pompe’s disease (OMIM 232300, glycogen storage disease type II) is an autosomal recessive lysosomal storage disorder due to over 400 mutations in the GAA gene, encoding for the acid α-glucosidase (GAA) enzyme." (PMID 41316280, 2025). "Pompe disease is an autosomal recessive metabolic disorder caused by acid alpha-glucosidase (GAA) deficiency." (PMID 40981304, 2025). "Background/Objectives: Glycogen storage disease type II, also known as Pompe disease (PD), is a rare autosomal recessive genetic disorder triggered by a deficiency in lysosomal acid α-glucosidase (GAA)." (PMID 40869986, 2025). "Pompe disease, a rare autosomal recessive disorder caused by mutations in the GAA gene, leads to a chronic and progressive pathology, predominantly featuring limb-girdle muscle weakness and respiratory failure." (PMID 38778310, 2024). "Pompe disease, classified as glycogen storage disease type II, arises from a deficiency in the acid alpha-glucosidase (GAA) enzyme, leading to glycogen accumulation in multiple tissues." (PMID 38500078, 2024). "Glycogen storage disease type II, also known as Pompe disease or acid maltase deficiency, is caused by a deficiency of acid α-glucosidase (GAA; EC 3.2.1.3), which hydrolyzes glycogen to glucose." (PMID 39445404, 2024). "The second AR metabolism condition is glycogen storage disease type II, also called Pompe disease, another AR disorder caused by deficiency of the lysosomal alpha-glucosidase." (PMID 38553482, 2024). "Pompe disease (PD) is a rare autosomal recessive lysosomal disorder caused by loss-of-function of the α-glucosidase (GAA) gene." (PMID 40225932, 2024).
Pompe disease (continued). "Pompe disease, also known as glycogen storage disease type II, is a rare autosomal‐recessive disorder caused by a deficiency of acidic α‐1,4‐glucosidase (GAA) which is crucial for converting glycogen to glucose within lysosomes." (PMID 38186848, 2024). "Clinical data of 5 children with infantile-type glycogen storage disease type II due to the acidic α-glucosidase (GAA) gene variants diagnosed and treated at Hebei Provincial Children’s Hospital from January 2018 to April 2020 were retrospectively analyzed." (PMID 39213226, 2024). "Pompe disease, a rare genetic disorder, results from a deficiency in the enzyme acid alpha-glucosidase (GAA), leading to glycogen accumulation in various tissues, particularly the muscles." (PMID 38715621, 2024). "Pompe disease (PD) is a glycogen disorder caused by the deficient activity of acid alpha-glucosidase (GAA)." (PMID 38425665, 2024). "Glycogen storage disease type II (GSD II, OMIM # 232300), Pompe disease, is an autosomal recessive myopathy caused by lysosomal acid α-glucosidase (GAA) deficiency, which results in accumulation of glycogen mostly in muscle cells." (PMID 37821981, 2023). "Pompe disease is a rare glycogen storage disorder caused by deficiency of the lysosomal enzyme acid alpha-glucosidase (GAA), leading to glycogen deposition in multiple tissues." (PMID 37542277, 2023). "Pompe disease (OMIM 232300, glycogen storage disease II) is an autosomal recessive disorder characterized by deficiency of acid α-glucosidase (GAA), an enzyme required for the breakdown of lysosomal glycogen." (PMID 38250073, 2023). "Pompe disease (PD), also known as glycogen storage disease type II, is a rare, autosomal recessive disorder of the metabolism characterized by the deficiency of the lysosomal enzyme acid-alpha-1,4-glucosidase (GAA) (EC 3.2.1.20)." (PMID 37653444, 2023). "Pompe disease (PD) is an autosomal recessive disorder caused by mutations in the GAA gene that lead to a deficiency in the acid alpha-glucosidase enzyme." (PMID 37759679, 2023). "Glycogen storage disease type II (Pompe disease: PD) is an autosomal recessive metabolic disorder caused by mutations of the GAA gene encoding lysosomal acid α-glucosidase." (PMID 37106898, 2023). "Pompe disease is a debilitating medical condition caused by a functional deficiency of lysosomal acid alpha-glucosidase (GAA)." (PMID 37085544, 2023). "Pompe disease (glycogen storage disease II), is a muscle disorder of autosomal recessive origin caused by mutations in the alpha-glucosity acid (GAA) gene that has been treated for years with enzyme replacement therapy." (PMID 35976325, 2022). "Glycogen storage disease type II (GSD‐II, OMIM#232300), or Pompe disease (PD), is an autosomal recessive disorder caused by mutations in the lysosomal enzyme acid α‐glucosidase (GAA)." (PMID 34850579, 2022). "Pompe disease is a severe disorder caused by loss of acid α‐glucosidase (GAA), leading to glycogen accumulation in tissues and neuromuscular and cardiac dysfunction." (PMID 34850579, 2022). "GSD II (MIM# 232300), also known as Pompe disease, caused by deficiency of the enzyme acid α-glucosidase encoded by GAA, presents as a progressive myopathy due to accumulation of glycogen in lysosomes and cell destruction." (PMID 36105079, 2022). "GAA encodes for lysosomal α-glucosidase, essential for degradation of glycogen to glucose in lysosomes, which is mutated in Pompe disease/Glycogen Storage Disease II (GSD2 (formerly LGMD2V); OMIM: 232300)." (PMID 34740639, 2022). "Pompe disease (glycogen storage disease type II) is an LSD caused by the deficiency of the lysosomal enzyme acid α-glucosidase (GAA)." (PMID 35662258, 2022). "Pompe disease is an autosomal recessive hereditary lysosomal disorder and correlated with acid α-glucosidase enzyme (GAA) deficiencies, which lead to accumulation of glycogen in all tissues, most notably in skeletal muscles." (PMID 35386406, 2022).
Pompe disease (continued). "Pompe disease is caused by deficiency of acid α-glucosidase (GAA), resulting in glycogen accumulation in various tissues, including cardiac and skeletal muscles and the central nervous system (CNS)." (PMID 36284764, 2022). "Pompe disease is a metabolic myopathy caused by mutations in the gene for GAA, the enzyme that degrades glycogen into glucose within the acidic milieu of the lysosome." (PMID 35775064, 2022). "Pompe disease (PD) is an inherited metabolic disorder caused by a deficiency of acid α-glucosidase (GAA), leading to lysosomal accumulation of glycogen, mainly in skeletal and cardiac muscles as well as the nervous system." (PMID 36138713, 2022). "GAA enzyme activity was repeated in blood at 6 months of age was found to be in the deficiency range seen in patients affected with Pompe disease (3.3 nmol/hr/mg protein; normal range = 23.1-232.0)." (PMID 36246652, 2022). "Pompe disease, an autosomal recessive disorder caused by deficient lysosomal acid α-glucosidase (GAA), is characterized by accumulation of intra-lysosomal glycogen in skeletal and oftentimes cardiac muscle." (PMID 36517654, 2022). "Multiple gene mutations that can trigger deficiencies of the lysosomal enzyme acid alpha-glucosidase (GAA) have been identified as potential causes of GAA deficiency." (PMID 35775064, 2022). "The first variant (c.1465G>A) found in Cangrande’s GAA gene is described in patients with late-onset Pompe disease and fully inhibits α-glucosidase maturation and activity." (PMID 34702906, 2021). "We previously reported a generic assay to identify variants that affect mRNA expression and splicing in Pompe disease, a monogenic disorder caused by deficiency of acid α-glucosidase (GAA)." (PMID 33168984, 2021). "Pompe disease, an autosomal recessive lysosomal storage disorder, is caused by deficiency of lysosomal acid alpha‐glucosidase (GAA)." (PMID 33977033, 2021). "Pompe disease (PD) is a glycogen storage disorder caused by deficient activity of acid alpha-glucosidase (GAA)." (PMID 34768348, 2021). "Pompe disease (glycogen storage disease type II, acid maltase deficiency) is a rare autosomal recessive neuromuscular disease that results from mutations in the GAA gene, which encodes the enzyme acid alpha-glucosidase (GAA)." (PMID 33625582, 2021). "Pompe disease (PD), also known as glycogen storage disease type II, is an inherited disorder caused by the deficiency of acid-α glucosidase (GAA)." (PMID 33933104, 2021). "Biallelic pathogenic mutations in GAA result in Pompe disease (glycogen storage disease type II), a phenotypically variable disorder characterized by lysosomal glycogen accumulation, progressive muscle weakness, and respiratory insufficiency." (PMID 33971197, 2021). "All had enzymatically confirmed GAA deficiency; additionally, in 85.3%, the diagnosis was confirmed by GAA gene analysis." (PMID 33543425, 2021). "Pompe disease is a panethnic autosomal recessive lysosomal storage disorder due to mutations in the acid alpha-glucosidase (GAA) gene encoding the lysosomal GAA enzyme." (PMID 34072668, 2021). "In Pompe disease, the deficiency of the lysosomal enzyme acid alpha-glucosidase (GAA) causes skeletal and cardiac muscle weakness, respiratory failure, and premature death." (PMID 33953320, 2021). "Acid alpha-glucosidase (GAA) is a lysosomal glycogen-catabolizing enzyme, the deficiency of which leads to Pompe disease." (PMID 33971197, 2021). "Pompe disease is caused by the accumulation of glycogen in the lysosomes due to a deficiency of the lysosomal acid-α-glucosidase (GAA) enzyme." (PMID 34072668, 2021). "Pompe disease is an autosomal recessive inherited metabolic disorder caused by a deficiency of the acid α-glucosidase (GAA)." (PMID 34922579, 2021). "Pompe disease is caused by pathogenic variants in the GAA gene, which encodes acid α-glucosidase (GAA), an enzyme responsible for glycogen breakdown in the lysosome." (PMID 31931849, 2020).
Pompe disease (continued). "Glycogen storage disease type II (OMIM 232300), also known as Pompe disease, is an autosomal recessive metabolic myopathy caused by mutations in the acid alpha-glucosidase (GAA) gene encoding the lysosomal enzyme GAA." (PMID 33375166, 2020). "Pompe disease, a genetic disorder caused by variants of the glucosidase alpha acid (GAA) gene, leads from acid alpha-glucosidase (GAA) deficiency." (PMID 33073026, 2020). "The deficiency of the lysosomal of α-glucosidase (GAA) in Pompe disease tissue, also known as type II glycogenosis and acid maltase deficiency, was identified in 1963." (PMID 33260301, 2020). "The diagnosis of Pompe disease is usually made based on the typical clinical presentation followed by the demonstration of deficiency of GAA enzyme activity in muscle, skin fibroblasts or more recently dried blood spots (DBS) as well as GAA mutation analysis." (PMID 33371305, 2020). "Pompe disease or glycogen storage disease type II is characterized by lysosomal glycogen accumulation, caused by a deficiency of α-glucosidase enzyme (encoded by GAA gene) resulting in cardiac and respiratory failure." (PMID 32375321, 2020). "Pompe disease is an autosomal recessive lysosomal storage disorder (LSD) caused by deficiency of lysosomal acid alpha-glucosidase (GAA)." (PMID 32290314, 2020). "Pompe disease is a glycogen storage disease caused by a deficiency in acid α-glucosidase (GAA), a hydrolase necessary for the degradation of lysosomal glycogen." (PMID 32214050, 2020). "Pompe disease, or glycogen storage disease type II, is a rare inherited metabolic disorder due to the deficiency of the enzyme acid alpha glucosidase (GAA), which normally breaks down the glycogen inside the lysosomes of various cellular types." (PMID 32505193, 2020). "Glycogen storage disease type II, also termed Pompe disease, is caused by mutations in the acid alpha-glucosidase (GAA) gene." (PMID 32971894, 2020). "Pompe disease is a rare glycogen storage disease caused by an autosomal recessive mutation resulting in deficiency of acid α-glucosidase (GAA), the enzyme responsible for breaking down lysosomal glycogen." (PMID 32214050, 2020). "In general, for babies with IOPD who have cardiac involvement, treatment with recombinant human GAA (rhGAA) is initiated immediately after confirmation of GAA deficiency and positive CRIM status, either by genotyping prediction or by western blot." (PMID 32352041, 2020). "Pompe disease is a lysosomal storage disorder caused by autosomal recessive mutations in the acid alpha-glucosidase (GAA) gene." (PMID 33375166, 2020). "Pompe disease is caused by mutations in the GAA gene, resulting in deficient lysosomal acid-α-glucosidase activity in patients, and a progressive decline in mobility and respiratory function." (PMID 32317649, 2020). "Pompe disease, or glycogen storage disease II is a rare, progressive disease leading to skeletal muscle weakness due to deficiency of the acid α-1,4-glucosidase enzyme (GAA)." (PMID 32012848, 2020). "Identification of variants in the acid α‐glucosidase (GAA) gene in Pompe disease provides valuable insights and systematic overviews are needed." (PMID 31342611, 2019). "Complete deficiency of the GAA enzyme, resulting in enzyme activity < 1% of normal, is associated with classic infantile Pompe disease." (PMID 31342611, 2019). "Pompe disease (OMIM 232300, glycogen storage disease type II or acid maltase deficiency) is an autosomal recessive disease, caused by an inborn defect of lysosomal acid α-glucosidase (GAA; Hers, 1963)." (PMID 31850350, 2019). "Pompe disease is an autosomal inherent genetic disease caused by mutations in the GAA gene that encodes acid alpha-glucosidase." (PMID 31026687, 2019). "Pompe disease, also known as glycogen storage disease type II, is a rare autosomal recessive disorder caused by mutations in the GAA gene that results in a deficiency of lysosomal acid α-glucosidase (GAA)." (PMID 31026687, 2019).